IGFBP3 (insulin like growth factor binding protein 3)
Diseases named in the same sentence as IGFBP3 in open-access papers (continued):
Sharing a sentence is not in itself a finding about the gene and the disease.
cardiovascular disease (13 papers, 2016 to 2025). "Proteins associated with lipid metabolism and cardiovascular health were also reduced, including ADIPOQ (also known as APM1, associated with cardiovascular disease) and IGFBP3 (a marker reflective of renal impairment)." (PMID 41301692, 2025). "Since the expression pattern of IGFBP3 in various cardiovascular diseases can vary depending on the underlying conditions, it is not accurate to simply state that increased IGFBP3 has cardioprotective effects." (PMID 37106699, 2023). "Besides, IGFBP3 (insulin like growth factor binding protein 3) is a well-known cardiovascular disease susceptibility gene." (PMID 35087571, 2021). "Of the six different circulating IGFBPs, IGFBP-3 is the most abundant, and it has been shown that low IGFBP-3 levels are associated with an increased risk of cardiovascular disease." (PMID 36960228, 2023). "Although IGFBP-3 levels were numerically higher in female compared to male participants in the Cardiovascular Health Study, to our knowledge, there have been no reports, so far, on sex differences in HFpEF or other cardiovascular diseases." (PMID 32831121, 2020).
metabolic disease (7 papers, 2011 to 2025). A congenital disorder (due to inherited enzyme abnormality) or acquired (due to failure of a metabolically important organ) disorder resulting from an abnormal metabolic process. "Thus IGFBP-3 interactions with H3 could unfold as an essential mechanism of gene expression in several metabolic diseases." (PMID 33401705, 2021).
kidney diseases (5 papers, 2021 to 2024). "In conclusion, this study provides evidence that elevated IGF-1 levels or the ratio of IGF-1/IGFBP-3 is associated with a higher risk of kidney disease progression and all-cause mortality." (PMID 37438734, 2023). "Compared with other IGFBPs, IGFBP-3 is involved in a wider range of kidney diseases." (PMID 35002740, 2021). "Additionally, the association between the plasma levels of NGAL, IGFBP-1, IGFBP-3, and IGFBP-4 in patients with DN were compared to those in patients with T2D without kidney disease and control participants." (PMID 35148702, 2022).
prostate (5 papers, 2011 to 2022). "We have demonstrated that the activation of the IGF-1R pathway through the increased expression of tissue-derived IGFs and the loss of IGFBP-3 is an early event in lung carcinogenesis." (PMID 26041671, 2015). "Identifying the regulation of stromal AR in IGFBP3 expression in Gli1-lineage FB is intriguing, suggesting an underlying mechanism for androgen-mediated IGF1 signaling activation in prostate oncogenesis." (PMID 36323713, 2022). "However, the expression of CAV1, IGFBP3 and TGFBR2 is decreased in PCa in general, suggesting a role in prostate carcinogenesis." (PMID 23185447, 2012).
adenocarcinoma (4 papers, 2007 to 2025). A common cancer characterized by the presence of malignant glandular cells. "IGF-1 factor is found to be more highly expressed in adenocarcinomas compared to adenomas and normal colon samples from patients, while IGFBP3 is lower in patients than in healthy individuals." (PMID 31480481, 2019). "However, IGFBP3 mRNA levels remained virtually unchanged in benign epithelium, PIN, and adenocarcinoma cells, indicating a pre-translational and/or post-translational modification of IGFBP-3." (PMID 17210081, 2007).
retinopathy (4 papers, 2011 to 2025). "Similarly, greater early macronutrient intake and growth velocity with higher insulin-like growth factor 1 (IGF-1) and insulin-like growth factor binding protein 3 (IGFBP3) levels have been associated with decreased retinopathy of prematurity severity." (PMID 31892145, 2019). "Despite these limitations, our findings indicated that the HIF1A and IGFBP3 genes could be used to confirm retinopathy disease progression in patients with DM." (PMID 40377287, 2025). "However, Igf1 and Igfbp3 mRNA expression in the liver was decreased more than 2-fold in the hyperglycemic oxygen-induced retinopathy pups (both P < 0.0001)." (PMID 33004691, 2020). "The mRNA expression profile at P17 was comparable to the expression at P12, with more than a 2-fold decrease of Igf1 and Igfbp3 in the hyperglycemic oxygen-induced retinopathy versus normoglycemic oxygen-induced retinopathy groups (both < 0.0001); Igfbp1 mRNA expression was the same in each group." (PMID 33004691, 2020).
heart disease (2 papers, 2017 to 2024). "Furthermore, understanding the potential interplay between IGFBP3, ISLR, SOST, and paracrine/autocrine response is a pivotal step in the identification of new or improved drug targets for the treatment of heart disease." (PMID 39430425, 2024).
mental disorders (2 papers, 2015 to 2021). A disease that has its basis in the disruption of mental process. "Plasma concentrations of BDNF, IGF-1 and IGFBP-3 in abstinent cocaine users grouped by diagnosis of common psychiatric disorders in substance users." (PMID 25734326, 2015).
inflammation (1 paper, 2023). Aberrant reaction of the microcirculation characterized by movement of fluid and leukocytes from the blood into extravascular tissues. "The IGF1/IGFBP3 ratio is the major predictor of liver inflammation in children with NAFLD." (PMID 37948568, 2023).
musculoskeletal diseases (1 paper, 2012). "Indeed, hypoxia is involved in the pathogenesis of several musculoskeletal diseases and is able to induce IGFBP-3 via HIF-1α in a wide range of cell cultures." (PMID 23036517, 2012).
neurological disorders (1 paper, 2021). "Moreover, the abnormal expression of IGFBP-3 was detected in patients with neurological disorders." (PMID 34452353, 2021).
skeletal dysplasia (1 paper, 2024). Any Mendelian diseases that affects growth and development of the skeleton. "Together, these data indicate that low IGF-1, IGFBP3, and IGFALS levels likely contribute to growth retardation and skeletal dysplasia in Tmem263-KO mice." (PMID 38241182, 2024). "Consequently, Tmem263 knockout (KO) mice had low circulating IGF-1 and IGF binding protein 3 (IGFBP3), leading to dramatic postnatal growth failure and skeletal dysplasia." (PMID 38241182, 2024).
IGFBP3 also shares sentences with these, for which no sentence is quoted: thyroid cancer (5 papers); benign prostatic hyperplasia (4); idiopathic pulmonary fibrosis (4); alcohol abuse (3); prostate adenocarcinoma (3); thalassemia (3); alcoholic hepatitis (2); autoimmune disease (2); benign tumors (2); carotid atherosclerosis (2); cholangiocarcinoma (2); congestive heart failure (2); endometrioid carcinoma (2); growth hormone insensitivity syndrome (2); Hypoinsulinemia (2); Intraventricular hemorrhage (2); mood disorder (2); sarcoma (2); systemic lupus erythematosus (2); varicocele (2); vitamin D deficiency (2); acute myeloid leukaemia (1); acute myocardial infarction (1); Adrenal insufficiency (1); aging (1); AIDS (1); alveolar rhabdomyosarcoma (1); anemia (1); anorexia nervosa (1); aortic aneurysm (1).
A further 99 diseases each share a sentence with IGFBP3 in 1 paper.